IL21 (interleukin 21)
Diseases named in the same sentence as IL21 in open-access papers (continued):
Sharing a sentence is not in itself a finding about the gene and the disease.
psoriasis (continued). "We also assessed functionality of the T cells by evaluating the secretion of several inflammatory cytokines (IL-17A, IFN-gamma, IL-2, IL-33, TNF-alpha, IL-21, IL-22, and IL-27), from cell-sorted purified CD4+ and CD8+ T cells isolated from lesional and unaffected skin biopsies of psoriasis patients." (PMID 23468834, 2013). "Developing IL-21 inhibitors or combination therapies may offer new hope for psoriasis patients, particularly those nonresponsive to current therapies targeting IL-17 and IL-23​." (PMID 40161116, 2025). "Dysfunctional Tregs in peripheral blood of patients with psoriasis have been reported showing that they have a phosphorylation and an aberrant activation of STAT3, which is due to the effects of pro-inflammatory cytokines, not only IL-6, but also IL-21 and IL-23." (PMID 36901778, 2023). "As our data showed that IL-21 was highly expressed in psoriasis patients and promoted the proliferation of CD4+ T cells and the differentiation of Th17, we then investigated the proportion of Th17 and Treg cells in the PBMCs derived from psoriasis patients and healthy individuals." (PMID 31440249, 2019). "Moreover, high levels of IL-21 protein and IL-21 mRNA are observed in lesional psoriasis skin compared to samples taken from non-lesional skin of the same patients and from healthy controls." (PMID 30065726, 2018). "In addition, the levels of IL-21, IL-17, and IFN-γ secreted by cTfh cells were all statistically increased in psoriasis patients as well, which was further proved that cTfh cells were activated in psoriasis." (PMID 27774460, 2016). "As IL-21 expression was markedly increased in psoriasis patients and could promote CD4+ T cell proliferation and Th17 cell differentiation and also inhibited the expression of Foxp3, we then measured the proportion of Th17 and Treg cells in the PBMCs of psoriasis patients." (PMID 31440249, 2019). "In this respect, it is interesting that in both psoriasis and SLE the LL37-specific Th17-cells do exist and express Ror-ɣt but only in SLE, and not in psoriasis, they can express the TFH-markers Bcl-6 and high IL-21, at polyclonal and clonal levels." (PMID 32245990, 2020).
viral infections (69 papers, 2011 to 2026). "Th17 cells were also associated with the control of several bacterial and viral infections and are a potential source of IL-21 that has been recently identified as a major helper cytokine during chronic viral infection." (PMID 23818845, 2013). "Moreover, a number of cytokines, including IL-6, IL-6R, IL-21 and IL-4, have been implicated in shaping immune responses after viral infection." (PMID 27447555, 2016). "Paired with IL-21, expanded cTfh cells following influenza vaccination resemble responses to natural viral infections with impacts on T and B cell maturation and function." (PMID 37063867, 2023). "During some viral infections, IL-21 has been reported to be less essential for acute humoral immunity due to compensation from other cytokines." (PMID 37870962, 2023). "In the future, I hope that treatment and vaccine development research for viral infections using the functions of IL-21 will progress, such as the development of therapeutic strategies that limit the action to immune cells such as B cells and CD8+ T cells." (PMID 34502427, 2021). "In general, IL-21 regulates the immune response to viral infections via CD4+ T cells, B cells and CD8+ T cells." (PMID 34502427, 2021). "Similar to other viral infections, IL-21 function is thought to be primarily focused on the recovery of exhausted CD8+ T cells." (PMID 34502427, 2021). "Interleukin-21 (IL-21) plays an important role in both innate and acquired immune responses, and its expression is significantly increased in a variety of viral infections." (PMID 34383171, 2021). "In this review, I will introduce the findings to date on how IL-21 is involved in some typical viral infections and the potential of treating viral diseases with IL-21." (PMID 34502427, 2021). "This review summarizes recent findings regarding the role of IL-21 in viral infection and treatment." (PMID 34502427, 2021). "Moreover, IL-21 is important for B cell differentiation and the antibody response, and loss of IL-21 signalling produces an obvious defect in the differentiation of long-lived plasma cells and in the maintenance of specific antibody levels during virus infection." (PMID 32873255, 2020). "In summary, this study highlights that WAT and in particular GWAT depots are an abundant source of IL-10 and IL-21 in the context of a viral infection." (PMID 32455939, 2020). "In PVM, lung CD4+ T cells constitutively express IL-21, and the number of IL-21+ CD4+ T cells increases following viral infection." (PMID 30969166, 2019). "This suggests that the availability of T-cell-derived IL-21 is essential for the maintenance of a chronic alloimmune response, conceptually parallel to its role in a chronic viral infection." (PMID 31756235, 2019). "IL-21 has also been shown to control both humoral and adaptive cellular responses to viral infections." (PMID 30969166, 2019). "Taken together, these results demonstrate that Tfh cells responding to chronic viral infection exhibit an enhanced and sustained capacity to coordinately produce both IL-10 and IL-21." (PMID 30487586, 2018). "A large body of literature documents that the magnitude of the CD8 T cell response during persistent viral infections is regulated, in part, by IL-21 and IL-2 produced by CD4 T cells." (PMID 30372487, 2018). "There are still arguments about the contribution of IL-21-induced activation of NK cells in the control of viral infection." (PMID 30223493, 2018). "Although the role of IL-21 signaling in the CD4 T cell response to viral infection remains imperfectly defined." (PMID 29511486, 2017). "CD8+ T cells have been shown to require IL-21 for protective responses in chronic viral infections in humans and mice, and are known to play some role in controlling erythrocytic-stage Plasmodium infections in mice." (PMID 25763578, 2015). "IL-21 stimulates T and B cell responses and is important for the control of chronic viral infections." (PMID 24669269, 2014).
viral infections (continued). "In this study we investigated the role of IL-21 and the IL-21R in innate immunity to virus infections using a murine vaginal HSV-2 infection model." (PMID 24358128, 2013). "Interleukin (IL) -21 is produced by Natural Killer T (NKT) cells and CD4+ T cells and is produced in response to virus infections, where IL-21 has been shown to be essential in adaptive immune responses." (PMID 24358128, 2013). "Strikingly, this virus-driven Treg cell expansion was much more pronounced and longer lasting in mice lacking IL-21R expression, which suggested that the pro-inflammatory cytokine IL-21 restricted the proliferation of Treg cells in viral infections." (PMID 23696736, 2013). "Other studies also conclude that IL-21 is important for the adaptive immune system to control chronic viral infection." (PMID 24358128, 2013). "The purpose of this study was to investigate the role of IL-21 and IL-21R in the innate immune response to a virus infection." (PMID 24358128, 2013). "The importance of cell-intrinsic IL-21R signaling for the maintenance of CD8+ T cell functionality has been well documented and is considered as the primary effect of IL-21 promoting the immune control of chronic viral infections." (PMID 23696736, 2013). "Nowadays, IL-21 is exploited in various clinical trials as a cancer immunotherapeutic agent or for the control of persistent viral infections such as HIV." (PMID 24023776, 2013). "A previous study demonstrated that IL-21 participates in the immune response of viral infection clearance in acute HBV infection." (PMID 23407366, 2013). "In vivo models also indicate that IL-21 is critical for containing chronic viral infections and preventing the deletion of high affinity antiviral CD8+ T cells." (PMID 22279573, 2012). "In the context of an acute viral infection, we observed complete redundancy in the roles for IL-6 and IL-21 in Tfh development at the peak of the effector CD4 T cell response." (PMID 21423809, 2011). "C57BL/6 or IL-21−/− mice were treated with a neutralizing monoclonal antibody against IL-6 throughout the course of an acute viral infection (lymphocytic choriomeningitis virus, LCMV)." (PMID 21423809, 2011). "IL-21 is released during viral infection and helps control persistent infection." (PMID 38429307, 2024). "Additionally, it is noteworthy that the infection in the respiratory system intriguingly downregulated the expression of interferon-beta (IFN-β), interleukin 21 (IL-21), and IL-6 in the bone tissue, which are vital for the clearance of virus infection." (PMID 35534483, 2022). "IL-21 is a crucial factor for the immunological control of viral infections." (PMID 35656032, 2022). "In addition, the increase in IL21-expressing T-cells resembles the profile of a chronic active viral infection, as proposed by Fahey and collaborators, who showed that viral persistence redirects T-cell differentiation towards the Tfh profile in animal models." (PMID 33603079, 2021). "In addition to regulating the immune response to tumor and viral infections, IL-21 also has a profound effect on the development of autoimmune and inflammatory diseases." (PMID 34502427, 2021). "Thus, IL-21 plays an extremely important role in viral infections, especially chronic viral infections." (PMID 34502427, 2021). "Differences in IL-21 expression are also observed in viral infection models." (PMID 34721405, 2021). "Furthermore, IL-21 suppresses the exhaustion of CD8+ T cells to maintain the immune response against chronic viral infections." (PMID 34502427, 2021). "Thus, IL-21 plays an extremely important role, namely the regulation of antibody production for the early convergence of acute viral infections and the recovery of exhausted T cells to resist chronic infections." (PMID 34502427, 2021).
viral infections (continued). "Also, several in vivo studies in animal models have demonstrated that IL-21 is vital for controlling chronic viral infections." (PMID 29511486, 2017). "Regardless, our findings suggest a dual importance of IL-21 for preventing T cell exhaustion during chronic viral infections, and demonstrate that IL-21 in addition to its known direct effects on antiviral T cells also partially alleviates the suppressive activity of Treg cells." (PMID 23696736, 2013). "Little attention has been paid to the effect IL-21 could have in innate immunity to virus infections." (PMID 24358128, 2013). "Cells belonging to the innate immune system such as epithelial cells, NK, NKT cells and macrophages express the functional heterodimer IL-21R and respond to IL-21, thus they are potential targets for IL-21 in the innate stages of a viral infection (day 1-3 p.i.)." (PMID 24358128, 2013). "Thus we next performed comparative studies to determine whether acute or chronic viral infection differentially supports the formation of IL-10+IL-21+ co-producing Tfh cells." (PMID 30487586, 2018). "Furthermore, because CD4 T-cell depletion in HLACs is driven by cell death of abortively infected CD4 T cells, the data also suggest that IL-21 might broadly inhibit both productive and abortive viral infection by IL-21." (PMID 26108174, 2015). "T-bet–expressing TH1 cells that secrete interferon-γ (IFN-γ) are known for their role in viral infections, and BCL-6 (B cell lymphoma 6)–expressing CD4+ TFH cells can secrete interleukin-21 (IL-21) and assist B cells." (PMID 41499515, 2026). "Studies have reported that IL-21 can mediate multiple biological processes by activating the PI3K/Akt pathways, including responses to viral infections and inflammation." (PMID 38263004, 2024). "IL-21 is involved in multiple biological processes via activating the JAK/STAT, MAPK and PI3K/Akt pathways, such as viral infections, autoimmune disorders, allergies, and cancer." (PMID 38263004, 2024). "We further included the analysis of peripheral CD45RAneg CD4+CXCR5+ CXCR3neg T follicular helper (Tfh) cells, since they produce large amounts of IL-21 cytokine to sustain both CD8 and B cell immunity during viral infections such as HIV-119,39,40." (PMID 39709477, 2024). "As anticipated, preclinical data suggests similar in vivo effects as IL-21 application has been shown to support CD4+ and CD8+ memory Tcell formation during amongst others viral infections." (PMID 29568345, 2018). "The functional heterodimer IL-21R is highly expressed by cells from the innate immune system and IL-21 is known to increase IFN-γ production and cytotoxicity of NK cells, which are important effector cells in early control of viral infections." (PMID 24358128, 2013). "Activated NK and NKT cells are important in the early defence against virus infection and in vitro NKT cells can produce substantial amounts of IL-21." (PMID 24358128, 2013). "Interestingly, evidence suggests that IL-21-producing CD4+ T cells may be critical for the maintenance of CD8+ T cell responses during chronic virus infections, although it remains to be determined whether in all these cases IL-21 is produced by Tfh cells or another T cell subset." (PMID 21943070, 2011). "In addition, IL‐21, which is critical for CD8+ T cells and B cells, increases during chronic viral infections as compared with acute viral infections." (PMID 37829505, 2023). "The acute and chronic phases of viral infections significantly increased CD27− B-cell population, which could be further expanded by IFN-γ and IL-21 signaling." (PMID 36505417, 2022).
viral infections (continued). "Our finding that transfection efficiency of T cells was enhanced by addition of IL-21 had not been matched with previous researches, which suggest that IL-21 has been investigated as a therapeutic modality in a number of viral infections, such as HIV." (PMID 34179083, 2021). "However, IL-21 also displays anti-viral effects, as mice models have shown that CD4+ T cell produced IL-21 is critical for the differentiation, function and survival of anti-viral CD8+ T cells able to contain chronic virus infections." (PMID 33228556, 2020). "Indeed, GC Tfh cells induced following viral infections, where Th1 inflammatory responses predominate, express Bcl-6, Tbx21, IFN-γ, and IL-21, consistent with the induction of Th1-type Tfh cells." (PMID 31827000, 2020). "Moreover, 2-DG treatments also significantly recovered the upregulated IL-21 production and IgD-CD138+ plasma B cell frequency challenged by virus infection." (PMID 31744227, 2019). "An elegant study demonstrated that IL-21 was required to control chronic but not acute viral infections in mice." (PMID 31756235, 2019). "Moreover, Suc treatments also significantly recovered the upregulated IL-21 production and IgD-CD138+ plasma B cell frequency challenged by virus infection." (PMID 31744227, 2019). "In the absence of IL-21, the proliferation of GC B cells is significantly curtailed at the later stage of viral infection." (PMID 30405612, 2018). "However, these CD4 T cells with the altered activation state acquire the capability of producing IL-21, a key cytokine that enhances the GC response and also supports the CD8 T cell response; both are required for control of the viral infection." (PMID 29734372, 2018). "We reasoned that a high proportion of baseline IL-21-producing PBMCs is likely a contributing factor for restoring the function of effector T cells in viral infections, as it was reported that the HCV patients with higher baseline serum IL-21 levels were more likely to achieve SVR." (PMID 27428948, 2016). "This indicates that the defect in IL-21 signaling that results in reduced viral infection is intrinsic to B cells and not due to a role for IL-21 signaling in CD4 T cells." (PMID 25875847, 2015). "The antiviral activity of IL-21 was independent of envelope tropism as IL-21 also suppressed R5-tropic HIV-1NL4-3 virus infection in HLACs." (PMID 26108174, 2015). "IL-21 is a member of the type I cytokine family and has many different immune-modulatory functions during acute and chronic virus infections, although its role in IAV infection has not been fully evaluated." (PMID 25849970, 2015). "To better understand counter-regulation of Treg cells by IL-2 and IL-21 in the absence of confounding virus dynamics, we delivered the IL-21 gene by hydrodynamic injection to IL-2ic treated mice in the absence of viral infection." (PMID 23696736, 2013). "The potential inflammatory mechanisms may be as follows: Tph cells are multifunctional, capable of secreting a variety of cytokines, including interleukin 21 (IL-21), IL-10, interferon g (IFN-g), thereby playing a role in controlling bacterial and viral infections within the body." (PMID 40144882, 2025). "Promising novel makers of autoimmune encephalitis were the CSF cytokines IL-21 and IP10 which may provide better delineation between viral infections and autoimmune encephalitis than conventional markers, potentially leading to more immediate diagnosis and management of these patients." (PMID 32116981, 2019). "During viral infection, TFH cells provide help signals to B cells for antibody affinity maturation through their expression of co-stimulatory ligands and cytokines, such as CD40L and IL-21, and direct immunoglobulin class switching to the antiviral IgG2a/c subclass by secreting IFN-γ." (PMID 29734372, 2018). "Currently, however it is not known whether IL-21 plays a significant role in innate immune responses to virus infections." (PMID 24358128, 2013).
viral infections (continued). "Interestingly, blockade of IL-21 has been reported to reduce the MRL-Faslpr disease, including lymphadenopathy, and this cytokine has been shown to support the survival and function of chronically-activated CD8+ T cells during a persistent viral infection." (PMID 22102903, 2011). "Moreover, the increase in IL‐21‐producing CD4+ T cells in participants with diabetes, which are important in providing B cell help and in enhancing the survival and function of cytotoxic CD8+ T cells upon vaccination or viral infection, was accompanied by a concomitant increase in IL‐10 production." (PMID 41367201, 2025). "Furthermore, LCMV-specific CD8+ T cells were depleted to a greater extent in mice with impaired IL-21 signaling, indicating that IL-21 produced by CD4+ T cells is necessary for sustained CD8+ T-cell effector activity and, consequently, for maintaining immunity to resolve persistent viral infection." (PMID 37649897, 2023). "Moreover, we have shown that in vitro activation of 4-1BB-costimulated CAR4 T cells upregulates IL-2 and IL-21, which are cytokines that augment the function of CD8+ T cells during viral infection, and thus may have contributed to the sustained CAR8 T cell response that we observed in vivo." (PMID 32454027, 2020). "Moreover, although humoral immune responses to viral infection could initially develop in the absence of IL-21, the generation of long-lived plasma cell responses was defective in the absence of IL-21." (PMID 30969166, 2019). "Importantly, multiple labs have found that the lack of either IL-21 alone or IL-6 alone did not substantially impact development of Tfh in vivo in the context of protein immunizations or viral infections." (PMID 21423809, 2011). "Correspondingly, mice lacking IL-21 or IL-21R show diminished CD8+ T cell clonal expansion, increased exhaustion, and persistent high serum viral titers, indicating that IL-21 directly acts on CD8+ T cells to limit chronic viral infections." (PMID 26966515, 2016).